CCDC167 (coiled-coil domain containing 167)
Synonyms: C6orf129; HSPC265; dJ153P14.2
Tractability: Antibody: UniProt predicts a signal peptide or a membrane-spanning region. PROTAC: ubiquitination databases record sites on it; its protein half-life has been measured.
Gene: Protein-coding gene on chromosome 6 (37,482,920 to 37,499,894, reverse strand). Ensembl gene ENSG00000198937.
Subcellular location: Membrane
Subcellular location (Human Protein Atlas): Cytosol
Gene Ontology:
Molecular function: protein binding
Cellular component: membrane
Genetic constraint (gnomAD): Loss-of-function variants: 15 observed, 13.3 expected, observed/expected ratio (o/e) 1.13, 90% interval 0.75 to 1.7. The upper end of that interval is the gene's LOEUF score, 1.7, which puts it in group 6 of 6, group 1 being the genes least tolerant of losing a copy. Missense variants: 121 observed, 125.06 expected, observed/expected ratio (o/e) 0.97, 90% interval 0.83 to 1.12. Synonymous variants: 52 observed, 51.38 expected, observed/expected ratio (o/e) 1.01, 90% interval 0.81 to 1.27.
Homologues: Orthologues: chimpanzee CCDC167 (99% identical), macaque CCDC167 (97% identical), pig CCDC167 (89% identical), rabbit CCDC167 (87% identical), rat Ccdc167 (85% identical), guinea pig CCDC167 (84% identical), dog CCDC167 (82% identical), mouse Ccdc167 (79% identical), tropical clawed frog ccdc167 (58% identical), zebrafish ccdc167 (39% identical).
Diseases named in the same sentence as CCDC167 in open-access papers:
CCDC167 is named in the same sentence as 8 diseases in open-access papers, as found by Europe PMC text mining. Sharing a sentence is not in itself a finding about the gene and the disease. The quoted sentences say what the papers report.
breast carcinoma (2 papers, 2021 to 2024). "All of these data implicated the significance of CCDC167 in the progression of breast cancer." (PMID 33461170, 2021). "Integrated analyses from this study showed that the CCDC167 expression level was higher in breast cancer." (PMID 33461170, 2021). "Meanwhile, we also investigated the effects of CCDC167 on the progression of breast cancer with an experimental approach." (PMID 33461170, 2021). "The role of CCDC167 in breast cancer has been less well studied, therefore, in the present study, we used co-expression analyses to reveal biological functions and information of possible mechanisms." (PMID 33461170, 2021). "Collectively, these findings suggest that CCDC167 has high potential as a therapeutic target for breast cancer." (PMID 33461170, 2021). "Co-expression profiles of CCDC167 from breast cancers were identified in the METABRIC and TCGA databases." (PMID 33461170, 2021). "Detailed mechanisms of the CCDC167 gene in breast cancer were explored by examining its co-expressed genes from TCGA and METABRIC databases." (PMID 33461170, 2021). "Integrating many kinds of databases including ONCOMINE, MetaCore, IPA, and Kaplan-Meier Plotter, we found that high expression levels of CCDC167 predicted poor prognoses of breast cancer patients." (PMID 33461170, 2021). "The bioinformatics analysis of breast cancer patient samples collectively provided clues to a potential role of CCDC167 during breast cancer development." (PMID 33461170, 2021). "TCGA and METABRIC databases were used to analyze potentially CCDC167-co-expressed genes in breast cancer." (PMID 33461170, 2021). "In conclusion, the present study demonstrated the crucial roles played by CCDC167 and its downstream signaling in breast cancer patients." (PMID 33461170, 2021). "CCDC167 expression has the potential to predict the survival of breast cancer patients and provide targets for further therapy." (PMID 33461170, 2021). "The high expression of CCDC167 in breast cancer patients was also correlated with worse survival in these public databases." (PMID 33461170, 2021). "We systematically investigated messenger (m)RNA expression of CCDC167 and the survival probability of ER+ breast cancer patients using a public high-throughput database." (PMID 33461170, 2021). "CCDC167 was reported to be significantly upregulated as a hub gene in the lungs of chloroprene-treated mice, and to be downregulated by multiple antitumor therapeutics in breast cancer patients." (PMID 38580753, 2024). "We further analyzed CCDC167 overexpression in breast cancer patients." (PMID 33461170, 2021). "Knockdown of CCDC167 attenuated aggressive breast cancer growth and proliferation." (PMID 33461170, 2021). "In addition, from both TCGA and METABRIC databases, we found that “cell cycle role of the anaphase-promoting complex (APC) in cell cycle regulation” was the most significantly regulated pathway by CCDC167 co-expression in breast cancer." (PMID 33461170, 2021). "Moreover, there was a correlation between CCDC167 and histological differentiation of breast cancer, with increasing expression levels of CCDC167 as tumors progressed from nuclear grade I to III." (PMID 33461170, 2021). "Based on the qPCR results, we also found that treatment with these compounds also significantly decreased CCDC167 mRNA expression, which suggested that these drugs may downregulate CCDC167 signaling in breast cancer progression." (PMID 33461170, 2021). "Furthermore, we found that CCDC167-co-expressed genes were also involved in cell cycle and ubiquitination pathways, highlighting their essential roles in breast cancer." (PMID 33461170, 2021). "Endogenous levels of CCDC167 differed in a variety of breast cancer cell lines." (PMID 33461170, 2021). "The current study focused on CCDC167 pathways and cell cycle-related signatures, and these findings suggest that CCDC167 could have high potency as targeted therapy for breast cancer." (PMID 33461170, 2021).
breast carcinoma (continued). "The CCDC167 gene was upregulated in breast cancer compared to normal tissues in 12 studies." (PMID 33461170, 2021). "Other compounds that act against CCDC167 could be new therapeutic agents for treating breast cancer patients." (PMID 33461170, 2021). "These CCDC167-related pathways could potentially be targeted for treating and preventing breast cancer." (PMID 33461170, 2021). "However, there is yet little knowledge of the role of CCDC167 in breast cancer development." (PMID 33461170, 2021). "We used a qPCR to detect CCDC167 mRNA levels, and results showed the highest expression of CCDC167 in MCF-7 cells compared to other breast cancer cell lines." (PMID 33461170, 2021). "Through high-throughput technology and bioinformatics screening, we revealed that coiled-coil domain-containing protein 167 (CCDC167) was upregulated in different types of tumors; however, the role of CCDC167 in the development of breast cancer still remains unclear." (PMID 33461170, 2021).
asthma (1 paper, 2024). "CCDC167 was associated with the majority of these predicted biological processes, emphasizing its central role in asthma." (PMID 38580753, 2024). "The observations made in vivo provide empirical support for our initial hypothesis that CCDC167 has the potential to serve as both a biomarker and a therapeutic target for asthma." (PMID 38580753, 2024). "In particular, the role of CCDC167 as a crucial factor and a possible therapeutic target for asthma was confirmed through experimentation on mice with OVA-induced asthma." (PMID 38580753, 2024). "In the present study, CCDC167 was silenced in OVA-induced asthmatic mice, and the inhibitory effect of CCDC167 silencing in asthma was confirmed by decreased inflammatory cytokines and an improvement in airway injuries." (PMID 38580753, 2024). "The expression of hub genes, including CCDC167, POSTN, SEC14L1, and SERPINB2, was significantly lower in healthy donors (controls) compared to asthma patients." (PMID 38580753, 2024). "However, the role of CCDC167 in the development of asthma still remains unclear." (PMID 38580753, 2024). "The predictive value of the hub genes was assessed using ROC curves, and the aero under curves for CCDC167, POSTN, SEC14L1, and SERPINB2 were approximately 0.79, 0.87, 0.86, and 0.89, respectively, supporting their sensitivity and specificity in asthma diagnosis." (PMID 38580753, 2024). "However, the functional roles of CCDC167 and SEC14L1 in the context of asthma have yet to be fully elucidated." (PMID 38580753, 2024). "Finally, CCDC167, POSTN, SEC14L1, and SERPINB2 were designated as the asthma hub genes because they were characterized by all three machine learning algorithms." (PMID 38580753, 2024).
breast ductal carcinoma (1 paper, 2021). "In the Richardson dataset, the CCDC167 gene and its co-expressed genes, such as SAC3D1, SPC24, CENPM and DEPDC1B, were substantially upregulated in breast ductal carcinoma compared to the normal group." (PMID 33461170, 2021).
invasive breast carcinoma (1 paper, 2021). A carcinoma that infiltrates the breast parenchyma. "We found that CCDC167 expression was upregulated in 18 of 33 datasets, including an invasive breast carcinoma (BRCA) dataset." (PMID 33461170, 2021).
invasive ductal carcinoma (1 paper, 2021). "A similar expression profile of CCDC167 was also found in the METABRIC dataset for invasive ductal carcinoma versus normal breast tissues and other subtypes." (PMID 33461170, 2021).
cancer (1 paper, 2021). A tumor composed of atypical neoplastic, often pleomorphic cells that invade other tissues. "Transcription expression levels of CCDC167 in 20 types of cancer were screened in the Oncomine database." (PMID 33461170, 2021). "In order to investigate the anti-proliferative effect of CCDC167 shRNA on human breast MCF-7 cancer cells, we first measured its cell proliferation ability." (PMID 33461170, 2021).
tumor (1 paper, 2025). "Subsequently, we performed quantitative reverse-transcription polymerase chain reaction (qRT-PCR) to examine the expression levels of the seven key prognostic genes—CEBPB, TANK, MAT2B, TMEM165, CCDC167, CYFIP1, and COX17—in the CEBPB+CAF prognostic model in the tumor tissues." (PMID 40145099, 2025).
CCDC167 also shares sentences with these, for which no sentence is quoted: colorectal adenocarcinoma (1 paper).